CHRNA4 (cholinergic receptor nicotinic alpha 4 subunit)
Description:
Component of neuronal acetylcholine receptors (nAChRs) that function as pentameric, ligand-gated cation channels with high calcium permeability among other activities. nAChRs are excitatory neurotrasnmitter receptors formed by a collection of nAChR subunits known to mediate synaptic transmission in the nervous system and the neuromuscular junction. Each nAchR subunit confers differential attributes to channel properties, including activation, deactivation and desensitization kinetics, pH sensitivity, cation permeability, and binding to allosteric modulators. CHRNA4 forms heteropentameric neuronal acetylcholine receptors with CHRNB2 and CHRNB4, as well as CHRNA5 and CHRNB3 as accesory subunits. Is the most abundant nAChR subtype expressed in the central nervous system. Found in two major stoichiometric forms,(CHRNA4)3:(CHRNB2)2 and (CHRNA4)2:(CHRNB2)3, the two stoichiometric forms differ in their unitary conductance, calcium permeability, ACh sensitivity and potentiation by divalent cation. Involved in the modulation of calcium-dependent signaling pathways, influences the release of neurotransmitters, including dopamine, glutamate and GABA (By similarity).
Synonyms: NACRA4; BFNC; EBN; EBN1; NACHR; NACHRA4
Tractability: Small molecule: an approved drug acts on it; a structure with a bound ligand is known; a high-quality ligand is known; it belongs to a druggable protein family. Antibody: its Gene Ontology location is reachable by antibodies, with high confidence; UniProt places it where antibodies can reach, with medium confidence; UniProt predicts a signal peptide or a membrane-spanning region. PROTAC: a small molecule that binds it is known.
Target class: Ion channel; Nicotinic acetylcholine receptor alpha subunit; Ligand-gated ion channel; Nicotinic acetylcholine receptor
Chemical probes: A-85380
Safety:
Unwanted effects reported when the protein is acted on. In parentheses: how it was acted on, where the effect was seen, and who reports it.
abuse potential (activation; cardiovascular system, central nervous system, pulmonary, gastrointestinal; source: Bowes et al. (2012))
analgesia (activation; cardiovascular system, central nervous system, pulmonary, gastrointestinal; source: Bowes et al. (2012))
apnoea (inhibition; cardiovascular system, central nervous system, pulmonary, gastrointestinal; source: Bowes et al. (2012))
constipation (inhibition; cardiovascular system, central nervous system, pulmonary, gastrointestinal; source: Bowes et al. (2012))
decreased blood pressure (inhibition; cardiovascular system, central nervous system, pulmonary, gastrointestinal; source: Bowes et al. (2012))
decreased heart rate (inhibition; cardiovascular system, central nervous system, pulmonary, gastrointestinal; source: Bowes et al. (2012))
increased heart rate (activation; cardiovascular system, central nervous system, pulmonary, gastrointestinal; source: Bowes et al. (2012))
muscle relaxation (inhibition; cardiovascular system, central nervous system, pulmonary, gastrointestinal; source: Bowes et al. (2012))
nausea (activation; cardiovascular system, central nervous system, pulmonary, gastrointestinal; source: Bowes et al. (2012))
palpitations (activation; cardiovascular system, central nervous system, pulmonary, gastrointestinal; source: Bowes et al. (2012))
paralysis (activation; cardiovascular system, central nervous system, pulmonary, gastrointestinal; source: Bowes et al. (2012))
alcoholism (source: ClinPGx)
nicotine dependence (source: ClinPGx)
nicotine withdrawal (source: ClinPGx)
successfully quit smoking (source: ClinPGx)
Gene: Protein-coding gene on chromosome 20 (63,343,223 to 63,378,401, reverse strand). Ensembl gene ENSG00000101204.
Subcellular location: Synaptic cell membrane; Cell membrane
Subcellular location (Human Protein Atlas): Vesicles
Pathways (Reactome):
Neuronal System: Highly calcium permeable nicotinic acetylcholine receptors; Highly calcium permeable postsynaptic nicotinic acetylcholine receptors; Highly sodium permeable postsynaptic acetylcholine nicotinic receptors
Gene Ontology:
Molecular function: acetylcholine receptor activity; acetylcholine-gated monoatomic cation-selective channel activity; protein binding; acetylcholine binding; ligand-gated monoatomic ion channel activity; neurotransmitter receptor activity; extracellular ligand-gated monoatomic ion channel activity; monoatomic ion channel activity; transmembrane signaling receptor activity
Biological process: acetylcholine receptor signaling pathway; behavioral response to nicotine; cognition; DNA repair; nervous system process; response to hypoxia; response to nicotine; response to oxidative stress; signal transduction; synaptic transmission, cholinergic; action potential; B cell activation; calcium ion transport; chemical synaptic transmission; inhibitory postsynaptic potential; membrane depolarization; monoatomic ion transmembrane transport; monoatomic ion transport; neuromuscular synaptic transmission; presynaptic modulation of chemical synaptic transmission; regulation of dopamine secretion; regulation of membrane potential; sensory perception of pain; excitatory postsynaptic potential
Cellular component: acetylcholine-gated channel complex; dendrite; external side of plasma membrane; membrane; neuron projection; neuronal cell body; plasma membrane; presynaptic membrane; synapse; synaptic membrane; dopaminergic synapse; postsynaptic membrane
Genetic constraint (gnomAD): Loss-of-function variants: 28 observed, 46.01 expected, observed/expected ratio (o/e) 0.61, 90% interval 0.45 to 0.83. The upper end of that interval is the gene's LOEUF score, 0.83, which puts it in group 3 of 6, group 1 being the genes least tolerant of losing a copy. Missense variants: 846 observed, 860.95 expected, observed/expected ratio (o/e) 0.98, 90% interval 0.93 to 1.04. Synonymous variants: 416 observed, 380.98 expected, observed/expected ratio (o/e) 1.09, 90% interval 1.01 to 1.18.
Gene-disease validity (ClinGen):
ClinGen rates the evidence that CHRNA4 causes each of these diseases.
familial sleep-related hypermotor epilepsy (autosomal dominant): Definitive. An instance of sleep-related hypermotor epilepsy that is caused by an inherited genomic modification in an individual.
Homologues: Orthologues: macaque CHRNA4 (96% identical), chimpanzee CHRNA4 (86% identical), dog CHRNA4 (85% identical), rat Chrna4 (85% identical), mouse Chrna4 (84% identical), guinea pig CHRNA4 (83% identical), pig CHRNA4 (79% identical), tropical clawed frog chrna4 (72% identical), rabbit CHRNA4 (70% identical), zebrafish chrna4b (60% identical), zebrafish chrna4a (53% identical). Paralogues in human: CHRNA2 (55% identical), CHRNA3 (44% identical), CHRNA6 (42% identical), CHRNB2 (38% identical), CHRNB3 (38% identical), CHRNA5 (37% identical), CHRNB4 (37% identical), CHRNA1 (36% identical), CHRNA7 (31% identical), CHRNB1 (30% identical), CHRNG (29% identical), CHRND (29% identical), and 33 more.
Diseases named in the same sentence as CHRNA4 in open-access papers:
CHRNA4 is named in the same sentence as 182 diseases in open-access papers, as found by Europe PMC text mining. Sharing a sentence is not in itself a finding about the gene and the disease. The quoted sentences say what the papers report.
nicotine dependence (68 papers, 2003 to 2025). Physical and psychological dependence on nicotine. "A study in the Chinese population indicated that CHRNA4 rs1044396 and rs1044397 were associated with nicotine dependence, and CHRNA4 rs1044396 with smoking initiation." (PMID 35222535, 2022). "Family-based association testing showed that rs1044396 of the CHRNA4 gene was significantly associated with a protective effect against nicotine addiction, similar to our results." (PMID 29240768, 2017). "We inspected the CHRNA5-CHRNA3-CHRNB4 cluster, the CHRNA6-CHRNB3 cluster and CHRNA4, which are genes showing confirmed association to nicotine dependence and smoking behaviours." (PMID 27957625, 2016). "Several rare CHRNA4 SNPs were negatively associated with nicotine dependence indicating its protective effect." (PMID 26106326, 2015). "Prior studies in humans have supported CHRNA4 as a susceptibility gene for nicotine dependence and other smoking behaviors." (PMID 26440539, 2015). "Genetic variation within exon 5 of the α4 subunit of nicotinic acetylcholine receptor (CHRNA4) gene can modulate the attention network function and was implicated in nicotine dependence." (PMID 26106326, 2015). "Using criteria for smoking behavior that encompass more than the single ‘cigarettes per day' item, we identified a common CHRNA4 variant with important regulatory properties that contributes to nicotine dependence and smoking-related consequences." (PMID 26440539, 2015). "Our results revealed that rs2273500, a splice site acceptor SNP with important regulatory effects for CHRNA4, was associated with risk of developing both nicotine dependence and lung cancer." (PMID 26440539, 2015). "We tested the 23 CHRNA4 SNPs/indels associated with nicotine dependence at P<5 × 10−5 for independent replication using 7469 ever smokers from five European-ancestry samples." (PMID 26440539, 2015). "In subjects from the Center on Antisocial Drug Dependence (CADD), the minor alleles of CHRNA4 risk polymorphisms (rs1044396 and rs1044394) are associated with a significantly greater propensity to develop nicotine dependence than otherwise." (PMID 25642160, 2014). "Positive associations between nicotine dependence and CHRNA4 were reported in case-control and family studies." (PMID 24498031, 2014). "Previous candidate gene association studies using six CHRNA4 SNPs found evidence for associations with measures of nicotine dependence in Chinese men, and females of European-American and African-American descent." (PMID 18618000, 2008). "Although rs1044396 of the CHRNA4 gene was associated with nicotine addiction and the addiction phenotype, further association, family-aggregation, or twin studies are needed to examine the extent to which IGD shares a common genetic vulnerability with substance addictions." (PMID 29240768, 2017). "Rare variants in CHRNA4 have also been implicated as contributing to nicotine dependence risk." (PMID 26440539, 2015). "Nonetheless, our new evidence revealing a common SNP with important regulatory features, along with a newly discovered functional rare variant, firmly establish CHRNA4 as an important susceptibility gene for nicotine dependence and its adverse health consequences." (PMID 26440539, 2015). "In male Japanese subjects, the CHRNB2 polymorphism (rs4845652) may confer protection against nicotine dependence, whereas a combination of this polymorphism with the CHRNA4 risk polymorphism (rs1044397) leads to higher nicotine dependence scores." (PMID 25642160, 2014). "Similar to the study in Japan, an early study with male Chinese smokers revealed that the CHRNA4 risk polymorphism (rs1044396) was significantly associated with age at smoking initiation and the CHRNA4 risk polymorphisms (rs1044396 and rs1044397) were associated with nicotine dependence." (PMID 25642160, 2014).
nicotine dependence (continued). "CHRNA4 encodes the cholinergic receptor nicotinic alpha 4 subunit, a nicotinic acetylcholine receptor (CHRNA4, n.d.), and the alternate allele in rs1044396 (a G > A variant) has been related to less nicotine dependence." (PMID 39845554, 2024). "Genetic factors, which are indicated in affecting nicotine dependence, include genetic variants of α3, α4 and α5 subunits of nicotinic receptors, which are encoded by CHRNA3, CHRNA4 and CHRNA5 genes, respectively." (PMID 35222535, 2022). "With respect to addiction, a biological link between CHRNA4 and the nicotine-addiction phenotype has been established." (PMID 29240768, 2017). "CHRNA4 has strong biological plausibility for influencing nicotine dependence and consequently its adverse health effects." (PMID 26440539, 2015). "Future studies with a large sample of brain-specific CHRNA4 exon-specific sequences and FTND measurements are needed to validate and elucidate the splicing mechanism involving rs2273500 and its effect on nicotine dependence risk." (PMID 26440539, 2015). "Further pharmacological studies are required to extend our knowledge on the role of CHRNA4 in the treatment of nicotine dependence." (PMID 24498031, 2014). "While there is converging evidence that exon 5 of CHRNA4 plays a role in normal attention, neuropsychiatric disorders and nicotine dependence, the rs1044396 C-T substitution in question results in synonymous translation." (PMID 21203548, 2010). "Regarding SNP coverage, our top nicotine dependence-associated CHRNA4 variants are 1000 Genomes–imputed SNPs not present on genotyping arrays or imputable from HapMap phase II in prior GWAS." (PMID 26440539, 2015). "We found genes related to nicotine addiction (CHRNA3, CHRNA4, CHRNA5), neurodegeneration (IREB2), chromosome maintenance (HIST1H2BD), mRNA stability (CSDC2), and transcriptional repression to be potentially affected by the pregnancy maternal smoking phenotype." (PMID 40074595, 2025).
lung carcinoma (51 papers, 2009 to 2025). "It is interesting to note that genes such as C5AR1, CHRNA4 and HTR1A from the neuroactive ligand receptor pathway have been reported in association with PAH, lung cancer, COPD and idiopathic pulmonary fibrosis." (PMID 31324852, 2019). "Importantly, several GWAS based on Caucasian populations have consistently identified 15q25 as lung cancer susceptibility region, which contains the nicotinic acetylcholine receptor subunit gene cluster, harboring CHRNA5, CHRNA3 and CHRNA4 genes." (PMID 23469231, 2013).
schizophrenia (44 papers, 2008 to 2025). A major psychotic disorder characterized by abnormalities in the perception or expression of reality. "Taken together, these results show that CHRM3 is strongly co-expressed with GABRG2, HRH3, and CHRNA4 (risk genes for psychotic disorders, epilepsy, and schizophrenia) in THAL and other brain tissues." (PMID 31740666, 2019). "In this study, we demonstrated that prenatal exposure to BP-3 caused substantial increase in Mef2c, Grin2a, and Chrna4 which corresponds to upregulation of these genes in brains of schizophrenia patients as detected in post-mortem." (PMID 30402708, 2019). "Non-coding single nucleotide polymorphisms within the nicotinic acetylcholine receptor alpha 4 subunit gene (CHRNA4) are robustly associated with various neurological and behavioral phenotypes including schizophrenia, cognition and smoking." (PMID 25934188, 2015). "Second, it suggests that genetic variation in exon 5 of CHRNA4 might be associated with schizophrenia per se or perhaps schizophrenia-related outcome measures like treatment response." (PMID 27054571, 2016). "Our work lays the ground for future studies on how synonymous CHRNA4 exon 5 SNPs affect cognitive processes and how they might be associated with neuropsychiatric disorders such as schizophrenia." (PMID 27054571, 2016). "In addition to the involvement of the CHRNA7 polymorphism in nAChR genes, in particular the D15S1360 associated with smoking by individuals with schizophrenia, there appears to be a significant association between the CHRNA4 rs3746372 allele 1 and smoking with a large number of cigarettes daily." (PMID 39370620, 2024). "A specific polymorphism in the CHRNA4 gene (gene coding for the nicotinic acetylcholine receptor subunit alpha 4, rs1044396) has been identified in individuals presenting with internet addiction, and a similar profile of genetic polymorphisms has been found in schizophrenia." (PMID 36698079, 2023). "In addition to motor hyperactivity, ADSHE families that carry the CHRNA4 and CHRNB2 mutations present cognitive disabilities, mental retardation, and schizophrenia-like symptoms." (PMID 37626860, 2023). "Thus, the specific participation of CHRNA4 in mechanisms of PPI in patients with schizophrenia could be proposed." (PMID 35846783, 2022). "Also, the effects of polymorphisms rs3746372 and rs1044396 in the CHRNA4 gene were only observed in schizophrenia, but not in controls." (PMID 35846783, 2022).
epilepsy (35 papers, 2009 to 2025). A brain disorder characterized by episodes of abnormally increased neuronal discharge resulting in transient episodes of sensory or motor neurological dysfunction, or psychic dysfunction. "The first epilepsy-associated gene, CHRNA4, was discovered in 1995, and thus CHRNA4-related autosomal dominant sleep-related hypermotor epilepsy (in today’s language) became the first “monogenic epilepsy”." (PMID 40381056, 2025). "CHRNA4 involved in the cholinergic synapse was the first identified epilepsy gene causing autosomal dominant nocturnal frontal-lobe epilepsy (ADFLE), which occurs mainly during NREM (non-rapid eye movement) sleep." (PMID 36835631, 2023). "Herein we describe a patient with SHE and a family history of epilepsy, identify a heterozygous variant in the CHRNA4 gene, and genetically reconstitute receptors harboring the altered α4 subunit." (PMID 36292983, 2022). "Acetylcholine Receptor Genes: A silent polymorphism 594C/T (rs121909580) in the cholinergic receptor nicotinic alpha 4 subunit (CHRNA4) gene is found with a higher frequency of T allele in epilepsy cases than control subjects." (PMID 33096746, 2020). "Subsequent next-generation genetic sequencing (Invitae Epilepsy Panel, 146 genes) revealed the heterozygous variant c.851C>G in the CHRNA4 gene resulting in the missense mutation p.Ser284Trp within the α4 subunit α4β2 nAChR, classified by the laboratory as a variant of uncertain significance." (PMID 36292983, 2022). "Indeed, it was identified in a genetically transmissible form of epilepsy (frontal-lobe epilepsy) that is associated with a mutation in the gene CHRNA4." (PMID 28758946, 2017). "This may suggest that, although CACNA1A contributes to epilepsy mutational load, the noise from other pathway-related genes (CHRNA4, KCNQ2, KCNQ3 and PLCB1) compromises this effect." (PMID 27984588, 2016). "Since the discovery of CHRNA4, gene discovery in the epilepsies has increased substantially, with recently published lists of “epilepsy-associated genes” typically including several hundreds of genes." (PMID 40381056, 2025). "The first epilepsy gene, CHRNA4 (cholinergic receptor nicotinic alpha 4 subunit), one of the genes responsible for focal epilepsy, was reported in 1995." (PMID 36835631, 2023). "Since identification of CHRNA4 gene, the first epilepsy gene in 1995, several studies have focused on developing reliable and potential markers of genetic polymorphism related to epilepsy." (PMID 34899152, 2021). "The HAR1A gene is considered an accelerated evolution gene for human brain development with molecular defects of the gene leading to psychotic and disruptive disorders; the genes CHRNA4 and KCNQ2 also deleted have been associated with ASD and epilepsy." (PMID 27651829, 2016). "Our model adds to the growing list of other specific human epilepsy knockin mice, including the Gabrg2, Kcnq2, Kcnq3, Scn1a and Chrna4 mice, to report a clear-cut genotype to phenotype seizure susceptibility." (PMID 19763161, 2009). "In addition to CHRNA7, several nAChR genes have been implicated in seizure disorders including CHRNA2, CHRNA4, CHRNB2." (PMID 40880366, 2025). "After searching in DrugBank, we retrieved a total of 47 anti-epileptic drugs and 151 targets, of which identified 17 target genes (CACNA1A, CHRNA4,CHRNA7,GABRA1,GABRA2,GABRB2,GABRG2,GRIK1,GRIN1,GRIN2B,KCNQ2,KCNQ3,SCN1A,SCN2A, SCN3A,SCN8A and SCN9A) were overlapped with risk genes of epilepsy." (PMID 36006933, 2022). "Transdermal nicotine treatment was successfully used in a CHRNA4-related case and carbamazepine in KCNQ2 and PRRT2 epilepsy." (PMID 33726816, 2021).